CD44 (CD44 molecule (IN blood group))
Diseases named in the same sentence as CD44 in open-access papers (continued):
Sharing a sentence is not in itself a finding about the gene and the disease.
tumor (continued). "T cells were gated for memory markers (CD62L and CD44) and CD4/CD8 ratio by gating on live singlet CD3+ T cells.The CD4/CD8 T cell ratio was compared between tumor bearing NCF1*/* and NCF1*/+ mice." (PMID 26076008, 2015). "Here, we discuss the prognostic role of CD44 and CD44v, its involvement in localization of CLL cells in lymphoid organs and tumor cell survival, and its suitability for therapeutic exploitation." (PMID 25941526, 2015). "CD44 mediates cell adhesion to the ECM, migration and is probably involved in tumor and metastasis initiation." (PMID 26617523, 2015). "CD44+ LAPC9 cells, however, when implanted subcutaneously or orthotopically in the dorsal prostate (DP), exhibited ∼6- and 19-fold, respectively, higher tumor-initiating potential than corresponding CD44− LAPC9 cells." (PMID 26246472, 2015). "CSCs are marker-positive, liver CSCs markers include CD13, CD24, CD44, CD90, CD133 and EpCAM, some of these markers are responsible for tumor highly invasive features and drug resistance." (PMID 26540347, 2015). "Overall, these results indicate that there is a complex relationship between the KAI1/CD82, CD44, MMP7 and β-catenin in tumor progression." (PMID 26408312, 2015). "On the other hand, miR-320 was reported to inhibit the Wnt/β-catenin pathway in PC3 and DU145 cells with concurrent reductions in the cell-derived xenograft tumor formation in NOD/SCID mice, as well as the CD44+ cell subpopulation, Oct4 and ABCG2 expression." (PMID 26593949, 2015). "We found that more than 99% of MDA-MB-435s were gated as CD44+ or CD44+/CD24Low, indicating that MDA-MB-435s cells are enriched of tumor initiating cells." (PMID 25605020, 2015). "Oligo-HA, competitively blocked binding of endogenous HMW-HA to CD44, consequently attenuating downstream signaling to the PI3K/Akt cell survival pathway, leading to inhibited tumor growth and apoptosis." (PMID 26029216, 2015). "After C666-1 tumor sphere growth analysis, the expression of SOX2 and CD44 by the spheroid cells was analyzed using confocal microscopy." (PMID 25897700, 2015). "The cell-surface protein CD47, together with CD44 and ALDH2, that were found up regulated at gene level in the CSCs subset, were also overexpressed in a high fraction of tumor cells." (PMID 26452033, 2015). "We showed that intraperitoneal injection of a monoclonal antibody directed against CD44 into nude mice carrying human pancreatic PDX previously treated with gemcitabine, resulted in tumor eradication." (PMID 26244163, 2015). "In solid tumors, c-Met+ and CD44+ cells demonstrate increased TISC gene expression profile, increased tumor-sphere formation, and efficient tumor initiation in limited dilution studies." (PMID 25886575, 2015). "Treatment with metformin resulted in a 2.2-fold decrease in the CD44+CD117+ population, suggesting that metformin targeted the CSC population within the tumor." (PMID 26718286, 2015). "It is thus evident from the results that the tumor cell growth and metastasis were significantly inhibited in the mice injected with CD117+CD44+-shHOTAIR compared with the mice injected with CD117+CD44+-scramble." (PMID 25792974, 2015). "We analyzed the clinical data of 139 BIDC cases retrospectively, detecting EGFR, CD44, and CD24 expressions in tumor tissue using immunohistochemistry." (PMID 25429827, 2015). "When we purified out CD44+/CD44− and α2β1+/α2β1− LAPC4 cells from the xenografts and performed similar LDA tumor experiments, surprisingly, the marker-positive and marker-negative subpopulations appeared similarly tumorigenic." (PMID 26246472, 2015). "Consistent with this concept, human prostate epithelial cells and malignant cells express PSC markers CD44, CD133 and/or integrin α2β1, and these prospective PCSCs generated xenograft tumors that resembled the original tumor." (PMID 25595909, 2015).
tumor (continued). "The basal-like CD44+CD90+ small cells at the stroma/tumor interface cross talk with surrounding CAFs, which provides an ideal niche for the growing tumor mass." (PMID 26000019, 2015). "Recently, miR-34a has been found to suppress the expression of CSC signature genes, such as CD44 and EMT markers, and to attenuate tumor invasion, metastasis formation, and CSC self-renewal capacity in pancreatic and glioma stem cells." (PMID 26064420, 2015). "Hyaluronan not only provides structural support to the tumor ECM but also interacts with cell surface receptors CD147/RHAMM and CD44." (PMID 26380222, 2015). "Among the 3 single surface marker (ABCG2, CD44, and α2β1) profiles, the ABCG2+ Du145 cell population (from either cultures or xenografts) manifested significantly higher tumor-regenerating activity than the ABCG2− population." (PMID 26246472, 2015). "The tumor-free survival rate was significantly higher for CD44 (−) GCTB patients than for CD44 (+) GCTB patients (P < 0.01) while the tumor-free survival rate was obviously lower for VEGF (+) GCTB patients than for VEGF (−) GCTB patients (P < 0.05)." (PMID 25929323, 2015). "3D-CSC subsets from in vivo tumor of control group manifest synchronous expression of TERT, CD29, CD44, CD90, CD105, CD133 and MUC-1 for renewable potential under spheroid-flow immunofluorescence scan." (PMID 26512920, 2015). "We then observed that combined HA-PEI/HA-PEG/MDR1 siRNA CD44 targeted nanoparticle and paclitaxel treatment decreased Pgp expression and increased apoptosis in MDR cells in tumor tissues from tumor-bearing mice." (PMID 25687880, 2015). "Like the CD44+ and CD44+α2β1+ cells, the LAPC9 SP cells self-renewed in vivo and a single LAPC9 SP cell was able to establish a 2° tumor." (PMID 26246472, 2015). "CD44 and receptor for HA-mediated motility (RHAMM) are the two main HA-receptors whose biological functions in human and murine inflammations and tumor cells have been investigated comprehensively." (PMID 25999946, 2015). "The in vivo growth inhibitory effect of liposomal CDF was evaluated in the nude mice xenograft tumor model of UM-SCC-1R and the inhibition of CD44 was measured." (PMID 26098778, 2015). "Prior to metastasis establishment, plentiful CSC-subsets (MUC-1+, CD44+, CD133+) with migrating potential were detected to drift from local tumor into the sentinel LNs (SLN) via natural lymph flux assay in dilated lymphatics/sinus in control group." (PMID 26512920, 2015). "A recent study based on 234 CRC patients have demonstrated that the increased CD44 expression in CRC is correlated with metastasis, increased early tumor recurrence and chemoresistance." (PMID 26010608, 2015). "The nude mice xenograft study showed a statistically significant tumor growth inhibition of UM-SCC-1R cells and a reduction in the expression of CD44 (p < 0.05), indicating an inhibitory effect of liposomal CDF on CSCs." (PMID 26098778, 2015). "MDA-MB-231 cells were pre-treated for 72 hours with GTCpFE, followed by washing and measurement of three well-established CSC endpoints: CD44+CD24− cell surface marker expression, MS formation, and xenograft tumor initiation." (PMID 26530254, 2015). "Results revealed a significantly lower expression of Vimentin, CD44 and ALDH1 and a higher expression of E-cadherin in tumor tissues generated from the IshikawashPiwil1 cells compared with IshikawaNT cells." (PMID 26506848, 2015). "Soluble CD44, probably shedding due to increased MMP-7 protease activity, promotes the effect further by inhibiting adhesion of tumor cells." (PMID 25885552, 2015). "Thus, the tumor-promoting ability of CD44 may be finely tuned to a particular disease condition." (PMID 26572077, 2015). "In the present study, we demonstrated that ICG-001 can reduce tumor sphere formation with concomitant reduction of both SOX2 and CD44 expression." (PMID 25897700, 2015).
tumor (continued). "Oligo-HA, generated by Hyal degradation, enhanced the cleavage of CD44 and its release into the ECM, which in turn enhanced tumor cell motility." (PMID 26029216, 2015). "In this model, cellular subpopulations within primary UC tumours were assigned to ‘differentiation states’ according to a correlated expression profile of cytokeratins (CK14, CK5, CK20) and surface markers (CD90, CD44, CD49f)." (PMID 26606927, 2015). "Overall, CD44 expression significantly correlated with five-year OS, five-year DSS, five-year DFS, Furhman grade, tumour recurrence and MVI." (PMID 26287771, 2015). "Our results showed that patients presenting with a tumor size of 5 cm or more, and a more advanced TNM stage, coupled with EMT expression and expression of cancer stem cell marker CD44, were prominent in early recurrence in the multivariate analysis." (PMID 25441488, 2014). "In a previous study, a high expression of CD44, particularly at the invasive front of the tumor, was identified in HNSCC tissue samples, where the tumor cells were in contact with their surrounding cells, including the stromal and endothelial cells." (PMID 24348826, 2014). "The feasibility of targeting CD271 to affect the viability of CD44+CD271+ cells in SCCHN and their capacity for tumor initiation is demonstrated by our study." (PMID 25149537, 2014). "In this study, we show that cells expressing CD271 in human and mouse SCCHN comprise a distinct subset of the CD44+ cells and that these CD44+CD271+ cells possess the greatest tumor-initiating capacity in this malignancy." (PMID 25149537, 2014). "Tumor-initiating cells (TICs) in squamous cell carcinoma of the head and neck (SCCHN) are best characterized by their surface expression of CD44." (PMID 25149537, 2014). "Next, CSC markers (CD133, CD44 and ALDH1) expression was examined for tumor formation capacity and the chemosensitization effect of curcumin on CSC markers in HCT116 3D high density tumor microenvironment co-cultures." (PMID 25238234, 2014). "To confirm our immuno-histochemical analysis of CD44, CD24, CD34, CD117 and Oct4 positive cells in orthotopic tumors, we performed Western blot analysis of the tumor extracts using specific antibody for markers detected by immuno-histochemical staining." (PMID 25264898, 2014). "Specifically, GASC and Gasc differ not only for the expression of stem-cell related markers such as CD133, but also in proteins involved in cell-cell adhesion processes and tumor growth: E-Cadherin (up-regulated in GASC), CD44 and CD105 (up-regulated in Gasc)." (PMID 25390644, 2014). "To assess the correlation between the expression of TAM and CSC markers in human OSCCs, we stained the tumor sections from human tissue arrays for OSCC with antibodies for CD68, CD163, SOX2, ALDH1, and CD44 and compared them with normal oral mucosa samples." (PMID 24883329, 2014). "This cell line has previously been demonstrated to sustain a subpopulation of CSCs with tumor initiating capacity characterized by the expression of the CD133 and CD44 surface markers even when grown in serum containing media." (PMID 24960044, 2014). "In addition, CD133, CD90, CD44, and Nestin co-expression may explain the tumorigenic potential of these cells, since Nestin and CD44 are also known as regulators of migration, invasion and tumor growth." (PMID 24432012, 2014). "We previously demonstrated that the low expression of favorable NB genes (EFNB2, EFNB3, EPHB6, NTRK1, CD44 and MIZ-1), as well as that of the tumor growth suppressive gene, EPHA2, in NB cell lines was due to epigenetic silencing." (PMID 24190252, 2014).
tumor (continued). "As we have shown, the majority of the established CR4 cells, as well as a significant proportion of cells from NOD/SCID mice tumor xenografts induced by these cells, express high levels of CD133, CD44, CD166, EpCAM and Lgr5." (PMID 24921652, 2014). "In CRC, recent studies have identified CD44+EpCAMhigh cells as CSC, which retain key stem cell properties and drive tumor growth." (PMID 24970802, 2014). "Biodistribution data demonstrated that polymersomes accumulated at the tumor site, due both to passive accumulation (EPR effect) and to active targeting (CD44 mediated endocytosis) in EAT-bearing mice." (PMID 24642908, 2014). "The BORIS-positive cells isolated using BORIS-molecular beacon, expressed higher telomerase hTERT, stem cell (NANOG, OCT4, SOX2) and cancer stem cell marker genes (CD44 and ALDH1) compared to the BORIS-negative tumor cells." (PMID 25279549, 2014). "Nonetheless, our data point to the ovarian CD44+CD117+ subset as a bona fide CSC population, which clearly differs molecularly and functionally from the bulk of differentiated tumor cells." (PMID 24946808, 2014). "The analysis showed that patients presenting with a tumor size of 5 cm or more, and a more advanced TNM stage, coupled with EMT expression and expression of cancer stem cell marker CD44, were prominent in early recurrence." (PMID 25441488, 2014). "Metformin treatment was found to specifically eliminate CD44+/CD24−/low CSCs and had a synergistic effect with doxorubicin, which resulted in reduced tumor burden and delayed tumor recurrence." (PMID 24527460, 2014). "Thus, CD44 might be served as a biomarker for tumor-initiating cells in GC." (PMID 24963492, 2014). "To screen for other markers of cancer stem cells in PTs, we harvested the BC-P007 xenografted tumor cells for FACS sorting using a panel of markers including CD29, CD44, CD90, CD117, CD 133, CD166, GD2, CD10, CD24 and ALDH." (PMID 24670249, 2014). "It was also found that CD133+, CD44+ and ALDH-high populations were enriched in tumor spheroids from the SKOV3 cells." (PMID 24959264, 2014). "In our study, HA enhanced both the pro-enzyme and active form of MMP-9 in GBC tumor cell supernatants as well as membrane-bound MMP-9 in membrane extracts (which may regulate pericellular ECM degradation from the tumor cell surface) in a CD44-dependent fashion in vitro." (PMID 24725816, 2014). "Expression of oncoproteins related to tumor metastasis, such as MMP2, MMP9, and CD44, was also significantly reduced." (PMID 24387290, 2014). "Decreased expression of CD44 and HER 2 implies depletion of tumor stem cells, and less tumorigenicity." (PMID 25485633, 2014). "Relationships between CD44 and CD24 protein expression levels and tumor parameters were analyzed and their prognostic values were evaluated by Cox proportional hazards models." (PMID 25212506, 2014). "Real-time qPCR analysis was performed, which showed a significant decrease in CD44 and increase in CK20 mRNA levels in tumor cells form metformin/FuOx-treated mice." (PMID 24465408, 2014). "In this study, exogenous or non-tumor derived PGE2 promoted tumor sphere formation and increment of SPCs and CD44+/CD133+ hCSCs in HCC cells." (PMID 24721996, 2014). "However, the role of CD44 variants in tumor progression and treatment resistance is not clear." (PMID 24122205, 2014). "Quantitative analysis indicated that the numbers of mammospheres from CD44+CD24− CSC were 5- or 9-fold greater than those from CD44+CD24+ and unsorted tumor cells (P < 0.05)." (PMID 25301732, 2014). "For example, high density of CD68 which is high-infiltration of tumor-associated macrophages was related with poorer outcome in node-negative breast cancer and CD44 positive patients showed longer overall survival and progression free survival than CD44 negative patients." (PMID 25075970, 2014).
tumor (continued). "Blocking Notch4 specifically using RNA interference reduces the number of CD44+/CD24−/ESA+ cells, suppresses mammosphere formation and completely inhibits tumor initiation whereas inhibiting Notch 1 has only a modest effect." (PMID 23593654, 2013). "We have previously shown that a novel Gemini vitamin D analog, BXL0124, down-regulated CD44 expression in MCF10DCIS cells and inhibited tumor growth in a MCF10DCIS xenograft." (PMID 23326564, 2013). "We also evaluated the correlation between the expression of CD44, CD133, or Sox2, and clinicopathologic factors including pathologic type, tumor/stromal cell ratio, and PCNA positive rate." (PMID 23874550, 2013). "CD44 is the binding site for hyaluronic acid, and CD24 is a receptor that interacts with P-selectin to induce metastasis and tumor progression." (PMID 23419168, 2013). "In contrast to CD44, L1CAM, and CD97, transplantation of Lin-CD24+CD29+ cells revealed a slight yet significant enrichment in tumour-initiating cells (estimated frequency of 1 in 56463, with CI of 399211 to 7986)." (PMID 24069241, 2013). "mRNA expression of CD44 was also measured for all conditions (IL-6, TNF-α, tumor spheroid, and plasma) via real time quantitative PCR (qPCR)." (PMID 23372803, 2013). "From 130 samples, 40 (30%) expressed this phenotype (CD44+/CD24-); of these, 37 were high-grade tumors (II and III) and lymph node metastases and only three samples were grade I neoplasms." (PMID 24119896, 2013). "Moreoever, CD44+/CD24- cells showed a unique surface ultrastructure by SEM and had the highest tumorigenic potential in tumor cell invasion and nude mouse xenograft assays." (PMID 23799994, 2013). "Here we demonstrate a hierarchical relationship between distinct subsets within CD44+CD24neg/low subpopulations from a TNBC line and from two TNBC patient-derived dissociated tumours (DTs)." (PMID 23982961, 2013). "CPE is cytotoxic to chemoresistant CD44+CSC/TICs, and CPE administration suppresses tumor progression in mice harboring CD44+ CSC/TICs-derived tumors." (PMID 23528891, 2013). "Here we show that cells with low level surface CD24 expression (CD24low+) and CD24 negative (CD24neg) cells comprise distinct phenotypes in the T-ISC-enriched CD44+CD24neg/low population of TNBC lines and primary dissociated tumour cultures." (PMID 23982961, 2013). "The data showed that the primary and metastatic tumor samples exhibited increased levels of ADAM17 expression and concomitant CD44 cleavage compared to normal controls." (PMID 24403253, 2013). "Although several studies have shown CD44 + and CD133 + cells initiate tumor growth at a significantly lower number of cells compared to the negative populations, CD44- and CD133- populations have also been reported be tumor initiating cells in some studies." (PMID 24160469, 2013). "Both the immunofluorescence staining and FACS analysis showed AT13387 significantly reduced the CD44 and SOX2 expression in C666-1 tumor spheres." (PMID 24156782, 2013). "When co-expression of CD44 and ALDH is examined by dual marker staining of xenograft tumor sections, there is tumor to tumor variability in the co-localization of these markers." (PMID 24019906, 2013). "We show that the pharmacologic targeting of STAT3 is able to suppress ALDH+ and ALDH+/CD44+/CD24− cells in vitro and in mouse tumor models." (PMID 24376586, 2013). "Our results clearly showed that AT13387 not only reduced the in vivo tumor formation, but also reduced the formation and growth of NPC tumor spheres accompanied by reduced expression of cancer stem-like cells markers CD44 and SOX2." (PMID 24156782, 2013). "The combination of CD44 and CD24 expression have been used to successfully enrich for CSCs in both cell line and tumor samples but caution must be exercised." (PMID 23986719, 2013). "We obtained four subtypes of tumor cells (i.e., CD44+/CD24-/low, CD44+/CD24+, CD44-/CD24+, and CD44-/CD24-)." (PMID 23799994, 2013).